MYC (MYC proto-oncogene, bHLH transcription factor)
Diseases named in the same sentence as MYC in open-access papers (continued):
Sharing a sentence is not in itself a finding about the gene and the disease.
tumor (continued). "Based on this, we hypothesize that a joint analysis of the different MB cell-types would better capture the local functional interactions of MYC and OTX2 across different tumor subtypes and would eventually help in delineating their global role in regulating metabolic processes in MB cells." (PMID 37016281, 2023). "Oncogenic pathways including MYC, mTOR, WNT/β-Catenin and NOTCH were significantly enriched in tumor tissues, and pathways involved in stress response including unfolded protein response, DNA repair and UV response were also significantly enriched in tumor tissues." (PMID 37205121, 2023). "The tumor cells were negative for MYC and BCL2 translocation." (PMID 37884941, 2023). "However, reducing c-MYC expression alone induces tumor regression in mouse models of PDAC; therefore, determining whether reducing c-MYC expression confers sensitivity to T/CQ is technically challenging." (PMID 36719686, 2023). "However, our dataset does not show a clear trend of an increased MYC expression with an increase in tumour grade." (PMID 37400829, 2023). "GSVA revealed that cell cycle-related pathways (e.g., MYC target and G2/M checkpoint), immune response pathways (e.g., IL-2 STAT5 signaling and TNF signaling via NF-κB), and aberrantly activated pathways (e.g., mTORC1 and PI3K/AKT/mTOR signaling) were dominant in tumor cells of APHC." (PMID 37336873, 2023). "To examine MYC stability, we treated tumor cells with a protein synthesis inhibitor cycloheximide (CHX) and found that both MYC and p-S62-MYC levels remained higher in the MYC-amplified D425 and non-MYC amplified D283 cells with CTDNEP1 knockdown than control-treated cells." (PMID 36765089, 2023). "While the inhibition of complex-I activity may play a role in the anti-tumor effects of IACS-010759 treatment, our findings demonstrate that the downregulation of MYC is a significant event that is important for determining the cell-fate of G3 MB cells in response to IACS-010759 treatment." (PMID 37130865, 2023). "MYC does not show altered expression patterns in correlation to tumour grade." (PMID 37400829, 2023). "Moreover, among the four major subgroups of MB, tumor recurrence due to survival of therapy-resistant cells in the residual tumor is more frequently observed in SHH MB and MYC-driven group 3 MB patients and, therefore, remains a major clinical challenge for MB treatment." (PMID 37190167, 2023). "In addition, histopathologic analyses showed that non-steatohepatitic tumor foci were developed in male c-MYC/AR-FL mice similar to hep-c-MYC/AR-V7 mice (c-MYC/AR-FL)." (PMID 36746917, 2023). "Furthermore, MYC increases SREBP1 transcription, and MYC cooperates with SREBP1 at these MYC-elevated levels to induce the transcription of lipogenic genes, thereby promoting MYC-induced tumorigenesis and tumor progression." (PMID 36755301, 2023). "Additional slides for these tumours were not available for re-analysis of MYC." (PMID 37113725, 2023). "CSCs in these tumours were somewhat different, the markers of which were PLP, Nestin, P75, GAP43, and Sox10, with GFAP, S100, and GAP43 (as a Schwann cell marker) in differentiated cells, in neurofibroma and MPNST; and Oct4, SOX2, Nanog, MYC, KLF4, CD133, CD44, and CXCR4 in CSCs of schwannoma." (PMID 37370764, 2023).
tumor (continued). "TNF-alpha signaling via NF-kB, IL6/JAK/STAT3 signaling, PI3K/AKT/mTOR signaling, MYC targets v2, TGF-beta signaling, and Kras signaling were mostly negatively correlated with LRRC3B expression, consistent with silencing of LRRC3B in tumor tissue, which may result in carcinogenesis." (PMID 36798137, 2023). "Cells in non-steatohepatitic tumor foci had scant cytoplasm without droplets of fat (c-MYC/AR-V7)." (PMID 36746917, 2023). "Concerning copy number aberrations (CNAs), the top amplified genes in the samples from the primary tumor were ERBB2 (6/19, 32%), AURKA, PPM1D (4/19, 21%), and FGFR1 (3/19, 16%), while in the metastatic samples ERBB2 (7/17, 41%), CDK12, FGFR1 (4/17, 24%), and AURKA, MDM4, MYC (3/17, 18%)." (PMID 36717329, 2023). "Moreover, CTDNEP1 knockdown led to significant increases in tumor sphere formation in both MYC amplified (D425) and non-MYC amplified (D283) G3-MB cell lines." (PMID 36765089, 2023). "It is now widely recognized that the MYC transcription factor is a dominant oncogenic driver in a majority of human T-ALL and is often activated downstream of NOTCH1, and targeting the NOTCH/MYC pathway can lead to cell death by increasing the apoptosis of tumor cells." (PMID 36691066, 2023). "Low expression of miR-1294 can up-regulate the expression of downstream protein-coding genes microtubule nucleation factor (TPX2), IGF1R, MYC proto-oncogene, bHLH transcription factor (c-Myc) and TRL4, TRL6, TRL8, TRL9, enolase 1 (ENO1), thereby promoting the proliferation of various tumor cells." (PMID 37303740, 2023). "HIF-1α decreases the level of MYC by inducing the transcription of MAX interactor 1 (MXI1) (a repressor of MYC) in cancer cells and enhances mitochondrial respiration but increases the glycolysis, leading to tumor growth and survival in a low oxygen environment." (PMID 35798726, 2022). "Conversely, the let-7 family, miR-34a, miR-145, and miR-29 targets are regarded as tumor suppressors and can inhibit tumor formation, proliferation, migration, spread, and angiogenesis by targeting many oncogenic transcription factors, including E2F1, K-RAS and c-MYC." (PMID 36532760, 2022). "Pre-clinically, the greatest sensitivity to ibrutinib was also seen in the co-amplified oesophageal models and thus future research may focus on evaluating ibrutinib efficacy in dual c-MYC and HER2 highly co-amplified tumours (3/7, 43% of the evaluable population in this study)." (PMID 35448150, 2022). "Indeed, a significant amplification of PVT1 alone was found in some tumour types, suggesting that increased PVT1 expression may be sufficient to increase MYC levels, which is crucial in tumorigenesis." (PMID 34754096, 2022). "However, expression levels of TOPK, c-MYC, and N-MYC were markedly increased only in tumor cells." (PMID 36970725, 2022). "Similarly to miR-9, miR-105 is also induced by the oncoprotein MYC in TNBC cells; this miRNA is subsequently encapsulated in extracellular vesicles and secreted by the tumor cell, then transferred in paracrine manner to CAFs, also causing activation of MYC pathway in these recipient cells." (PMID 35076579, 2022). "Combination of OTX015 with panobinostat further significantly suppressed tumor growth/weight by 48% (compared to OTX015) and 17.6% (compared to panobinostat), suggesting the antitumor potential of OTX015 combined with panobinostat, against MYC-driven MB in vivo." (PMID 36357906, 2022). "Second, we did not evaluate the cell of origin, BCL2/MYC expression, and/or tumor translocation." (PMID 35846027, 2022). "The expression of MYC, NR5A2, and SNAI1 was found to be higher in EC-adjacent tissues than in samples from cancer-free patients, which shows that tumor-surrounding tissues presented truly elevated expression, not just higher expression than in a tumor because of a decreased tumor expression." (PMID 36140779, 2022).
tumor (continued). "Importantly, c-MYC is considered as a critical target of IGF2BPs, and lncRNAs recruits or binds to IGF2BP1 to stabilize or increase the mRNA of c-MYC, depending m6A modification in tumor progression." (PMID 35541906, 2022). "Despite compelling pre-clinical rationale harnessing bench-to-bedside research and an opportunity to re-purpose an existing approved drug, ibrutinib did not demonstrate radiological tumour shrinkage as per RECIST 1.1 in pre-treated patients with c-MYC and/or HER2 amplified advanced OG cancer." (PMID 35448150, 2022). "In addition, we did not detect changes in the transcription factor c-MYC upon USP25 depletion, which has previously been linked to HIF activity and tumor metabolism." (PMID 35440539, 2022). "Indeed, signatures for stromal fibroblasts (estimate), extracellular matrix remodelling (KEGG) and focal adhesions (KEGG) were significantly higher in PM than in the corresponding primary tumours, while expression of WNT signalling target genes and MYC target genes was significantly lower." (PMID 35194192, 2022). "In line with this, the MYC transcriptional program enhanced by HFD in a murine PCa model was mediated by metabolic alterations that favoured the histone H4K20 hypomethylation at the promoter regions of MYC regulated genes, leading to increased cellular proliferation and tumour burden." (PMID 35215499, 2022). "The targeting of MYC transcription and PI3K activity impaired CR-CSphCs’ viability and clonogenic capacity, even in the presence of microenvironmental cytokines, and stabilized tumor xenograft growth, supporting the use of this combinatorial treatment for advanced CRC patient management." (PMID 35158939, 2022). "Since up-regulation of c-MYC is a hallmark of CRCs, it is therefore tempting to speculate that CRCs harbor comparatively high levels of DNA damage due to elevated expression of c-MYC, which results in a requirement of MDC1 up-regulation for tumor initiation and progression." (PMID 35624466, 2022). "In addition, we defined genes being expressed by all three MYC tumor groups, but absent in SHH tumors (e.g., Ogn, Tpm2, and Rarres1)." (PMID 35318328, 2022). "Vice versa, typical SHH marker genes are not expressed by tumor cells of all three MYC subtypes." (PMID 35318328, 2022). "We show co-occurrence of amplifications in MYC and genes from the PI3K pathway in HGSOC and other CIN-driver tumours and that inhibition of the activated mTOR survival pathway in the context of MYC-amplified tumours should be considered in future clinical trials." (PMID 36289203, 2022). "These so-called non-oncogene addictions or collateral sensitivities in cancer cells have been shown to be viable therapeutic strategies for the killing of tumor cells with non-targetable oncogenes (e.g. MYC) or those that have gained resistance to targeted therapy." (PMID 36480552, 2022). "In fact, gene set enrichment analysis (GSEA) of RNA-sequencing (RNA-seq) data from isolated MYC-expressing Cdk9-suppressed tumor cells (but not controls) showed reversal of signatures associated with MYC expression and ribosome biogenesis as was observed in orthotopic models." (PMID 35442775, 2022). "Interestingly, four tumor samples harbor duplications of only the enhancer region without the SOX2 gene, reminiscent of our previous findings regarding duplications of MYC and KLF5 enhancers." (PMID 34880227, 2021).
tumor (continued). "We stably co-expressed NrasV12 and c-MYC oncogenes in the livers of different mouse strains (e.g., CBA/CaJNarl, C57BL/6Jnarl, and C3H/HeNCrNarl strains) with the same approach and observed a dramatic divergence in both tumor latency and tumor burdens among these mouse strains." (PMID 34502289, 2021). "Notably, these mutants had no impact on the proliferative potential of MYC, further emphasising the importance of the pro-apoptotic capacity of this oncogene in tumour surveillance." (PMID 33799592, 2021). "Certain miRNA also functions as tumor suppressors, for instance, the let 7 family suppresses tumor development and metastasis via targeting key oncogenic genes like high-mobility group AT-hook 2 (HMGA2), members of the RAS family (NRAS, KRAS, and HRAS), and MYC." (PMID 35145899, 2021). "We identify genes connected to mitochondrial function and ribosome biogenesis as direct MYC/HCF-1 targets and demonstrate how modulation of the MYC–HCF-1 interaction influences cell growth, metabolite profiles, global gene expression patterns, and tumor growth in vivo." (PMID 33416496, 2021). "Thus, in the absence of an intact immune system, MYC inactivation fails to elicit complete and sustained tumor regression and eventually a tumor recurs due to the resistance to MYC inactivation and the restoration of MYC expression." (PMID 33446671, 2021). "Although MYC and E2F1 are two well-studied oncogenic transcription factors that are frequently dysregulated in PCa cells, whether the two genes together with TERT have synergistic effects on tumor severity are still unclear." (PMID 34858826, 2021). "Furthermore, to investigate whether LINC01001 regulates crizotinib-resistant NSCLC tumor growth via MYC, pcDNA-LINC01001 and sh-MYC plasmids were co-transfected into H1299/R cells to overexpress LINC01001 and knockdown MYC, respectively." (PMID 34630126, 2021). "In support of our finding, mechanisms other than MYC/MYCN downregulation contribute to BETi activity, because inhibition of cell proliferation has been reported even with no reduction, or even an increase, of these transcription factors in lines from different tumor types." (PMID 33668642, 2021). "Sample F16 could now be classified as “double-hit” (DH) for MYC and BCL2 rearrangements, sample F67 as a MYC and BCL6 DH tumor (with partners IGH and IGL), sample F194 as MYC and BCL2 and BCL6 triple hit (TH, although MYC and BCL6 fused together) and sample F209 as TH." (PMID 34099699, 2021). "This reconciles the genome invasion phenotype observed upon MYC overexpression (which is mainly driven by non-sequence-specific binding), with the persistence of selective (and sequence-specific) transactivation observed in tumor cells." (PMID 34201047, 2021). "Wnt signalling target gene c-MYC mRNA fold-changes were significantly higher in tumour cells compared with normal (p < 0.001) but did not significantly differ between treatment groups, although with a smaller mean fold-change in intravenous 3.2 (1.90–4.50 95% CI) versus oral 4.7 (4.50–8.20 95% CI)." (PMID 34211054, 2021). "MYC is another well-known oncogene, which could be activated by E2F1 in tumor." (PMID 33791304, 2021). "However, when the MYC and HCF-1 attachments in the cancer cells were disrupted, the tumours shrunk." (PMID 33416496, 2021). "Although in most cases, there is a positive correlation between MYC-amplification and sensitivity to BETis, surprisingly, tumours lacking MYC amplification respond to the BETi treatment similarly to those with MYC amplification, suggesting that there are other targets within a cell for BETis." (PMID 34681760, 2021).
tumor (continued). "The current study did not identify high level copy gains in any tumor, consistent with previous findings; however, 54% of tumors harbored equivocal copy gains, and 18% demonstrated copy gains suggestive of amplification in MYC." (PMID 34445161, 2021). "Small nucleolar RNA host gene 12 (SNHG12), a direct transcriptional target of c-MYC that may promote cell migration by regulating MMP13 expression, has been found to be significantly upregulated in TNBC, its levels correlating with tumor size and presence of lymph node metastasis." (PMID 33572395, 2021). "In these studies, suppression of MYC has proven to induce tumor regression not only in those tumors considered MYC-driven, but also in those in which MYC is not the initiating oncogenic lesion, suggesting that MYC inhibition would represent an effective treatment for many cancer types." (PMID 35582389, 2021). "Notably, targeting components of Pol I using the selective inhibitor CX5461 to treat tumors with MYC amplification has shown the selective killing of tumor cells through the activation of non-canonical ATM signaling." (PMID 34359683, 2021). "Therefore, MYC-immortalized MSCs are not tumorigenic and sEVs from these MSCs do not promote tumor growth." (PMID 33918628, 2021). "In this study, we presented evidence that miR-30d functions as a tumor-suppressive molecule, directly or indirectly targeting key glycolytic genes independent of oncogenic transcription factors HIF1a and MYC, and rewiring the cellular metabolism to reduce glycolysis and repress PDAC tumorigenesis." (PMID 34021267, 2021). "This indicates that MYC is not always amplified in 8q24 chromosome region in 8q-amplified but other oncogenes residing in chromosome 8q24 might play a role in tumor progression." (PMID 34830903, 2021). "Strategies to inhibit MYC signal might potentially convert a non-T cell inflamed tumor into a T cell inflamed tumor, importantly, improve outcomes." (PMID 34544424, 2021). "Besides, NOTCH and MYC are differentially involved in BCAA metabolism in tumor and muscle, and enhanced lipid synthesis is independent of BCAA catabolism." (PMID 33882453, 2021). "As a tumor suppressor or tumor promoter, miR-let-7b has been found to halt cell proliferation, adhesion, and invasion by targeting Protein Code Gene (PKA1), Diaphanous Related Formin 2 (DIAPH2), Radixin (RDX), RAS, MYC, and High Mobility Group A2 (HMGA2) genes and their respective proteins." (PMID 34122072, 2021). "In vitro, FL stromal cells decrease tumor B cell apoptosis through a set of partially resolved mechanisms, including the production of hedgehog ligands (Hh), BAFF and TGF-β, over- expression of ABC-type multi-drug transporters, and activation of a c-MYC/HDAC6 loop in tumor cells." (PMID 34956214, 2021). "It is reported that spermine synthase (SMS), in cooperation with MYC, can maintain CRC cell survival, so the combined inhibition of SMS and MYC signaling may be a promising strategy for inducing synergistic apoptosis and tumor regression." (PMID 33193630, 2020). "Interestingly, the lactate produced in cancer cells by increased glycolysis, which may be present in the tumor microenvironment, promotes glutamine metabolism by a HIF2 and MYC-dependent mechanism." (PMID 33008042, 2020). "Although it remains speculative, it is possible that in this patient CNV in all 3 exons of MYC may not originate from the primary tumor, but rather from circulating tumor cells, which have a deleterious impact on outcome in UCB25." (PMID 33298978, 2020).